MIR34AHG (MIR34A host gene)
Synonyms: lnc34a
Gene: Long non-coding RNA gene on chromosome 1 (9,139,555 to 9,202,826, reverse strand). Ensembl gene ENSG00000228526.
Gene Ontology:
Biological process: miRNA-mediated post-transcriptional gene silencing
Diseases named in the same sentence as MIR34AHG in open-access papers:
MIR34AHG is named in the same sentence as 7 diseases in open-access papers, as found by Europe PMC text mining. Sharing a sentence is not in itself a finding about the gene and the disease. The quoted sentences say what the papers report.
renal carcinoma (1 paper, 2024). A carcinoma arising from the epithelium of the renal parenchyma or the renal pelvis. "The TCGA database analysis revealed the differential expression of 7 DElncRNAs namely GAS6-AS1, MIAT, LINC00921, MMP25-AS1, C22orf34, MIR34AHG, and MIR4435-2HG in 4 distinct pathological subtypes of renal cancer." (PMID 39213211, 2024).
MIR34AHG also shares sentences with these, for which no sentence is quoted: cancer (4 papers); colon cancer (4); tumor (4); hepatocellular carcinoma (2); myocardial infarction (1); pancreatic cancer (1).